BCL6 (BCL6 transcription repressor)
Diseases named in the same sentence as BCL6 in open-access papers (continued):
Sharing a sentence is not in itself a finding about the gene and the disease.
osteosarcoma (7 papers, 2006 to 2025). A usually aggressive malignant bone-forming mesenchymal neoplasm, predominantly affecting adolescents and young adults. "The inhibitory effect of miR-101 on osteosarcoma cell invasion and migration was rescued by restoration of BCL6 expression." (PMID 31903129, 2020). "The correlation between miR-101 and BCL6 expression was also investigated in the 15 osteosarcoma specimens, and the results showed that miR-101 expression was inversely correlated with BCL6 mRNA expression." (PMID 31903129, 2020). "Our data confirm the existence of a miR-101/BCL6 axis for the first time, as well as the oncogenic role of BCL6 in osteosarcoma." (PMID 31903129, 2020). "In contrast to the function of miR-101, BCL6 significantly enhanced osteosarcoma cell invasion and migration, and ectopic expression of BCL6 rescued the suppression of osteosarcoma cell invasion and migration induced by miR-101." (PMID 31903129, 2020). "In summary, we have demonstrated that miR-101 is a definitive suppressor of osteosarcoma invasiveness and metastasis, and these effects are mediated, at least in part, through regulation of BCL6." (PMID 31903129, 2020). "Our results showed that miR-101 expression was inversely correlated with BCL6 expression in osteosarcoma tissue samples." (PMID 31903129, 2020). "This supported by the findings in previous study, which described that an interaction of Tax with the POZ domain of BCL6 enhances the repressive activity of BCL6 and increased the levels of apoptosis induced by BCL6 in osteosarcoma cells." (PMID 22726420, 2012). "Moreover, in vitro experiments using osteosarcoma cells stably expressing miR-101 showed decreased BCL6 mRNA and protein expression, and BCL6 was demonstrated to be a novel target of miR-101 by a dual-luciferase reporter assay." (PMID 31903129, 2020). "The potential synergistic function between oncogene BCL6 and EZH2 in osteosarcoma requires further investigation." (PMID 31903129, 2020). "Besides these, we found KLF4, STAT3, BCL6, TFAP2A, and TFAP4 as potential drivers of osteosarcoma metastasis." (PMID 37938582, 2023). "Accordingly, we observed under transcriptional starvation and following cell damage with etoposide that BCL11A-XL and BCL6 re-localized to nucleoli in U2OS osteosarcoma cells (data not shown)." (PMID 16704730, 2006). "In addition, qRT-PCR analysis of BCL6 expression in 15 pairs of matched osteosarcoma tissues and adjacent normal tissues showed increased BCL6 mRNA levels in osteosarcoma tissues compared to adjacent normal tissues." (PMID 31903129, 2020).
asthma (6 papers, 2008 to 2026). "A GWAS of asthma symptoms in 1,246 children in the population of Salvador, Brazil, was carried out; they found that BCL11A is associated with hematopoietic symptoms of asthma, and it may be related to its interaction with BCL 6 and participation in hematopoietic cell differentiation." (PMID 35712670, 2022). "We also investigated the effect of T cells overexpressing BCL6 on the development of asthma by transferring splenic CD4 T cells from sensitized mice into nontreated BCL6-Wt B6 mice." (PMID 23282478, 2008). "In contrast to our expectation, 6 asthma SNPs showed nominal association with lower eosinophil counts in the general population (rs1233578 [ZBED9], rs519973 [BCL6], rs7686660 [USP38], rs6691738 [TNFSF4], rs2507978 [HLA‐B], rs3117098 [HCG23]), and 1 SNP in the asthma population (rs2786098 [CRB1])." (PMID 37186423, 2023). "Recently, we studied the roles of BCL6 in T cells in the development of asthma." (PMID 23282478, 2008). "Therefore, BCL6 may prevent the development of asthma by attenuating Th2 cytokine production in an experimental murine model, and failure of BCL6 repressor activity may be involved in the initiation and/or exacerbation of asthma in humans." (PMID 23282478, 2008).
Hepatic steatosis (6 papers, 2019 to 2025). Steatosis is a term used to denote lipid accumulation within hepatocytes. "On the contrary, it has been reported that in mice fed HFD, Bcl6 knockout in the liver attenuated the hepatic steatosis." (PMID 40211057, 2025). "Our findings indicate that BCL6 hepatocyte deletion worsens in vivo hepatic steatosis and inflammatory infiltration, while barely affects liver fibrosis." (PMID 35436984, 2022). "Hepatic BCL6 knockout promoted TG accumulation in the liver of healthy mice, while BCL6 overexpression attenuated the severity of fatty liver in obese mice." (PMID 35436984, 2022). "Mechanistically, the translocase fatty acid CD36 was determined to be a transcriptional target of BCL6 that influences its role in hepatic steatosis." (PMID 35436984, 2022). "With these models, we noted that BCL6 overexpression improved insulin resistance and hepatic steatosis in mice models maintained on a HFD diet." (PMID 35436984, 2022). "Interpreted as a whole, BCL6 overexpression in hepatocytes alleviates in vivo hepatic steatosis and inflammatory infiltration, while barely affects liver fibrosis." (PMID 35436984, 2022). "Considering that BCL6 is widely involved in the progression of NAFLD as well as the fact that fatty liver previously demonstrates markedly reduced BCL6 expression, we speculate that aberrant BCL6 expression may have an important influence on NAFLD." (PMID 35436984, 2022). "This study finds transcription factor BCL6 to be a critical key regulator of fatty liver disease." (PMID 35436984, 2022). "Indeed, knockouts and various knockin mutants of NCoR, SMRT, and HDAC3 have demonstrated hepatic steatosis phenotypes, in contrast to the lipid overload-protected phenotype observed here with hepatocyte Bcl6 ablation." (PMID 30983568, 2019). "Curcumin ameliorated hepatic steatosis and insulin resistance by downregulating the hepatic c-Jun N-terminal kinase 2 (JNK2)/Fork head box protein O1(FOXO1)/B-cell lymphoma 6 (Bcl6) axis and altering the composition and structure of the intestinal flora." (PMID 41368575, 2025). "In addition, IR and hepatic steatosis were observed to improve in mice fed with high fat diet (HFD) that overexpressed BCL6 protein levels, while MASLD conditions were aggravated in those mice where BCL6 protein levels were downregulated." (PMID 40211057, 2025).
lymph node metastasis (6 papers, 2009 to 2024). "Furthermore, there was a strong correlation between BCL6 expression and important clinical indicators such as FIGO staging, lymph node metastasis, and recurrence." (PMID 38169532, 2024).
preeclampsia (6 papers, 2013 to 2020). Preeclampsia is a hypertensive disorder of pregnancy that is characterized by new-onset hypertension with proteinuria presenting after 20 weeks of gestation, and depending on mild or severe forms may initially present with severe headache, visual disturbances, and hyperreflexia. "While deregulated BCL6 is linked to lymphomagenesis by blocking lymphocyte terminal differentiation, increased BCL6 in the placenta contributes to the development of preeclampsia by impairing trophoblast differentiation and fusion." (PMID 29312557, 2017). "Further investigations are needed to delineate the exact working mechanisms by which deregulated BCL6 contributes to the development of preeclampsia." (PMID 33182312, 2020). "BCL6, a gene previously found to be up-regulated in the placenta in preterm preeclampsia, represses trophoblast differentiation and is regulated by stress-activated protein kinase signaling pathways." (PMID 30135684, 2018). "A permutation test showed that BCL6 overexpression in ischemia mimicked overall expression changes of module M1 and M2 genes in preterm preeclampsia, while ARNT2 overexpression in ischemia (and also in hypoxia) mimicked the up-regulation of module M2 genes in term and preterm preeclampsia." (PMID 30135684, 2018). "While deregulated BCL6 is linked to lymphomagenesis by suppressing DNA damage response and blocking terminal differentiation, increased BCL6 in the placenta, observed independently by several groups, contributes to the development of preeclampsia by impairing trophoblast differentiation and fusion." (PMID 29312557, 2017). "Alternating O2 concentrations combined with ARNT2 or BCL6 overexpression led to the dysregulation of 11 genes (5 in the M2 and 3 in the M1 modules), including LEP, FLT1, and ENG, similar to preeclampsia." (PMID 30135684, 2018). "Three CpGs (Chr3:187,458,095, Chr3:187,458,163, and Chr3:187,458,327) were differentially methylated in preeclampsia, of which CpG Chr3:187,458,163 was differentially methylated in preterm preeclampsia, suggesting that this CpG may have a role in BCL6 dysregulation in preeclampsia." (PMID 30135684, 2018). "Among the transcription regulatory genes in module M2, ARNT2, BCL6, and JUNB were highly expressed in preterm but not in term preeclampsia, suggesting that these might play a role only in the pathology of preterm cases." (PMID 30135684, 2018).
T-cell lymphomas (6 papers, 2012 to 2024). "The up-regulation of IL1A was previously shown in EBV-positive NK/T-cell lymphomas along with mRNAs of other genes thought to be involved in cell proliferation such as BCL6 or ERBB4." (PMID 22870299, 2012). "A computational analysis indicated the BCL6-3′-UTR as a potential target amongst others for miR-205 which was found here to be down-regulated in the EBV-positive NK/T-cell lymphomas and the EBV-negative samples as compared to normal tissue." (PMID 22870299, 2012). "More recently, BCL6 was also found to play a role in the development of T-cell lymphomas." (PMID 22870299, 2012). "To further analyse the differential expression of BCL6 in nasal NK/T-cell lymphoma vs. primary tissue, we compared the expression levels of BCL6 in CD56+ cells derived from two healthy donors with the mRNA levels in the EBV-positive cell lines SNK6, SNT10 and NK-92." (PMID 22870299, 2012). "Our data showed that the K607E mutation in BCOR—which results in the protein being unable to bind to BCL6— significantly enhanced cell proliferation, AKT phosphorylation, and IL-2 production in T cell lymphoma lines." (PMID 33468080, 2021). "A previous study had determined the mRNA expression profile of EBV-infected nasal NK/T-cell lymphoma lines and found, among others, the IL1A, BCL6, CD44 and c-FOS genes to be induced and the interleukin 1 receptor 1 (IL1R1) gene to be repressed compared to normal lymphocytes." (PMID 22870299, 2012).
B-cell neoplasm (5 papers, 2018 to 2025). A group of heterogeneous lymphoid tumors generally expressing one or more B-cell antigens or representing malignant transformations of B-lymphocytes. "Like other mature B cell neoplasms, FL expresses pan-B cell antigens (CD19, CD22, CD79a and PAX5), and is also by definition positive for germinal center markers, such as BCL6, HGAL and LMO2." (PMID 34898578, 2021).
esophageal cancer (5 papers, 2009 to 2025). A primary or metastatic malignant neoplasm involving the esophagus. "As BCL6 was recently shown to be one of the 12 stromal genes that can distinguish preinvasive from invasive disease in esophageal carcinoma based on profiling of the microdissected stroma only, we have selected this gene for validation in pancreatic tissues." (PMID 23372777, 2013). "We also evaluated endogenous BCL6 expression in human colon and oesophageal cancer cell lines by western blotting." (PMID 19337254, 2009).
ischemic stroke (5 papers, 2010 to 2025). A stroke disorder caused by obstruction of blood flow to the brain, due to thrombotic (local blood clot formation) or embolic (due to a blood clot or other material traveling from another site) event. "Coincidentally, it has been suggested that NEAT1 alleviate ischemic stroke inhibiting NLRP3 mediated via miR-10b-5p/BCL6 axis." (PMID 36941678, 2023). "bcl6 is induced in circulated leukocytes after ischemic stroke, but its precise role in this condition is unknown." (PMID 23800383, 2013). "However, many genes associated with ischemic stroke are not affected by tPA including BCL6, F5, and LY96 which were previously found to be predictive of ischemic stroke in humans." (PMID 20406488, 2010). "The lncRNA NEAT1 regulates NLRP3 inflammasome activation in microglia by forming a NEAT1/miR-10b-5p/BCL6/NLRP3 axis, thereby mitigating the harmful outcomes of ischemic stroke-induced inflammation." (PMID 39847586, 2025).
neuroblastoma (5 papers, 2004 to 2023). Neuroblastoma (NB) is the most common solid, extracranial childhood tumor. "However, BCL6 expression in the neuroblastic regions of neuroblastoma tumors was associated with enhanced relapse time and increased overall patient survival compared to regions without BCL6 expression." (PMID 37835497, 2023). "In neuroblastoma cell lines, differential BCL6 mRNA expression has been recorded between neuroblastic (N-type) and Schwannian stromal (S-type) cells, being higher in S-type cells." (PMID 37835497, 2023). "The data obtained in our experiments suggested differential expression of genes such as myb, CBFβ and HMG 1, 3 and 4 proteins with high expression restricted to the pre-B cells while Bcl-6 appeared to be over-expressed specifically in neuroblastoma cells." (PMID 15544702, 2004). "Hence, BCL6 is tagged by MYCN binding, a profile that mechanistically is in line with its transcriptional upregulation in MYCN-amplified neuroblastoma cells." (PMID 37835497, 2023).
acute myeloid leukemia (4 papers, 2022 to 2024). Acute myeloid leukemia (AML) is a group of neoplasms arising from precursor cells committed to the myeloid cell-line differentiation. "B cell lymphoma 6 (BCL6) is a transcriptional repressor and proto-oncogene that can maintain the survival and self-renewal of primary human acute myeloid leukemia cells." (PMID 36211454, 2022). "BCL6 is expressed at high levels in acute myeloid leukemia (AML) cell lines and primary AML cells, including aggressive AML." (PMID 39456751, 2024).
allergies (4 papers, 2008 to 2025). "In these cells, BCL6 contributes to the negative regulation of various key genes that predispose patients to allergies." (PMID 23282478, 2008). "Although the molecular mechanisms underlying these phenotypes are largely unknown, studies in BCL6-deficient mice have suggested that BCL6 functions to prevent the development or attenuate the pathogenesis of allergic diseases." (PMID 23282478, 2008). "The association between LPP and allergy may be mediated by an effect on the expression of BCL6 (B cell lymphoma 6), a transcription factor that represses the STAT6-mediated response to IL-4 and IL-13 and IgE class switching and inhibits Th2 cell differentiation in a mouse model." (PMID 32082391, 2020). "This study shows BBR regulates IgE in human tonsil cells by inhibiting STAT6 binding through BCL6 at the IgEh promoter showing its potential for treating IgE-mediated allergies." (PMID 40277916, 2025). "Transcriptional repressor B-cell lymphoma 6 (Bcl6) appears to regulate TH2 immune responses in allergies, but its precise role is unclear." (PMID 29696026, 2018). "In this article, we review the functions of BCL6 in allergic diseases by focusing on recent data from our laboratories and from other groups." (PMID 23282478, 2008). "Tissue hypereosinophilia occurs with increased IL-4, IL-5, and IL-13 production in B-cell lymphoma 6 (Bcl6)-knockout (KO) mice, suggesting that Bcl6 participates in allergy pathogenesis and that it may be important for reducing TH2 immune responses." (PMID 29696026, 2018). "Further genetic and functional analyses are needed to clarify whether BCL6 is related to the pathogenesis of allergic diseases, with the ultimate goal of establishing more effective means of prophylaxis and therapy." (PMID 23282478, 2008). "Given that a failure of immune homeostasis leads to the development of allergic diseases, BCL6 may play an important part in such diseases, acting as an inhibitor or protector." (PMID 23282478, 2008). "Therefore, the IL-33/Bcl6 axis might participate in allergy pathology via the regulation of Il4 in MPT cells to promote disease development in MPTH2 and NAMTH2 cells, contributing to the maintenance and exacerbation of disease pathology." (PMID 29696026, 2018). "In allergic diseases, IL-4-controlled transcriptional regulatory processes might be physiologically regulated by dual molecules, including activators such as STATs and repressors such as BCL6." (PMID 23282478, 2008). "Thus, an imbalance between STAT6 and BCL6 may be critically involved in the development of allergic diseases because BCL6 contributes to the function of a wide range of cells, including T cells, B cells, macrophages, mast cells, and airway epithelial cells." (PMID 23282478, 2008). "Thus, BCL6 apparently contributes to negative regulation of various central molecules such as cytokines, in particular Th2 cytokines, CC chemokines, and immunoglobulin E in allergic diseases." (PMID 23282478, 2008). "Bcl6 is a critical regulator of IL-4 production by MPT and MPTH2 cells in TH2 immune responses related to the pathogenesis of allergies." (PMID 29696026, 2018). "Recently, we reported that a TH2-promoting factor, namely, IL-33-mediated breakdown of Bcl6 in NAMTH2 cells, is likely involved in allergies given the effect of IL-33 on both MPT and NAMTH2 cells." (PMID 29696026, 2018). "Therefore, BCL6 might be a key regulator of IL-18 production by macrophages in allergic diseases." (PMID 23282478, 2008). "Therefore, BCL6 may be a major molecular target for Th2-type allergic diseases." (PMID 23282478, 2008). "Therefore, BCL6 may be a molecular target for Th2-type allergic diseases." (PMID 23282478, 2008). "Because Bcl6 expression is extremely high in CNS2-active MPT cells, we hypothesized that Bcl6 regulates allergen-mediated MPT cell activation in TH2 cell-dependent allergies." (PMID 29696026, 2018).
anaplastic large cell lymphoma (4 papers, 2009 to 2022). Anaplastic large cell lymphoma (ALCL) is a rare and aggressive peripheral T-cell non-Hodgkin lymphoma, belonging to the group of CD30-positive lymphoproliferative disorders, which affects lymph nodes and extranodal sites. "The frequency of mutations was similar to other reported cases of somatic hypermutations found in Rho/TTF, MYC and BCL6 in large-cell lymphomas (MF was from 0.12 for MYC to 0.69 for BCL6)." (PMID 19478941, 2009). "Furthermore, BCL6 is also expressed in the malignant T-cells of AITL, anaplastic large cell lymphoma (ALCL), and follicular helper T cells (Tfh cells)." (PMID 33468080, 2021).
angioimmunoblastic T-cell lymphoma (4 papers, 2019 to 2025). A mature T-cell non-Hodgkin lymphoma, characterized by systemic disease and a polymorphous infiltrate involving lymph nodes and extranodal sites. "On the other hand, most angioimmunoblastic T-cell lymphoma (AITL) cases express Tfh signature genes such as BCL6 in addition to PD-1 and CXCL13." (PMID 37788648, 2024). "Angioimmunoblastic T-cell lymphoma (AITL) has unique pathological features, including polymorphic tumor cells, accompanied by obvious vascular proliferation and increased immunoblasts, and often expresses markers such as CD10 and BCL-6." (PMID 40170733, 2025).